ODF1 (outer dense fiber of sperm tails 1)
Description:
Component of the outer dense fibers (ODF) of spermatozoa. ODF are filamentous structures located on the outside of the axoneme in the midpiece and principal piece of the mammalian sperm tail and may help to maintain the passive elastic structures and elastic recoil of the sperm tail.
Synonyms: HspB10; ODFP; ODFPG; ODF27; RT7; CT133; ODF; ODFPGA; ODFPGB; SODF
Tractability: No criterion of Open Targets' tractability assessment is met for any kind of drug.
Gene: Protein-coding gene on chromosome 8 (102,551,589 to 102,561,018, forward strand). Ensembl gene ENSG00000155087.
Subcellular location: Cell projection, cilium, flagellum; Cytoplasm, cytoskeleton; Cytoplasm, cytoskeleton, microtubule organizing center, centrosome
Subcellular location (Human Protein Atlas): Connecting piece; Flagellar centriole; Mid piece
Gene Ontology:
Molecular function: protein binding
Cellular component: nucleus; manchette; outer dense fiber; sperm flagellum; centrosome; cytoskeleton; motile cilium; polymeric cytoskeletal fiber
Genetic constraint (gnomAD): Loss-of-function variants: 10 observed, 23.56 expected, observed/expected ratio (o/e) 0.42, 90% interval 0.26 to 0.72. The upper end of that interval is the gene's LOEUF score, 0.72, which puts it in group 2 of 6, group 1 being the genes least tolerant of losing a copy. Missense variants: 271 observed, 315.34 expected, observed/expected ratio (o/e) 0.86, 90% interval 0.78 to 0.95. Synonymous variants: 114 observed, 124.97 expected, observed/expected ratio (o/e) 0.91, 90% interval 0.78 to 1.07.
Homologues: Orthologues: pig ODF1 (98% identical), rabbit ODF1 (98% identical), macaque ODF1 (97% identical), chimpanzee ODF1 (97% identical), rat Odf1 (93% identical), mouse Odf1 (90% identical), guinea pig ODF1 (89% identical).
Diseases named in the same sentence as ODF1 in open-access papers:
ODF1 is named in the same sentence as 13 diseases in open-access papers, as found by Europe PMC text mining. Sharing a sentence is not in itself a finding about the gene and the disease. The quoted sentences say what the papers report.
male infertility (10 papers, 2015 to 2023). The inability of the male to effect fertilization of an ovum after a specified period of unprotected intercourse. "The depletion of ODF1 by homologous recombination in mice causes male infertility due to sperm decapitation." (PMID 36142191, 2022). "Recently, ODF1 deficiency was identified as a factor in idiopathic male infertility." (PMID 36142191, 2022). "Depletion of the major outer dense fiber protein 1 (ODF1) mainly caused decapitation and male infertility but validated binding partners collaborating in the formation of sperm-specific structures are largely unknown." (PMID 31475146, 2019). "Depletion of ODF1 caused sperm decapitation and male infertility in mice." (PMID 31475146, 2019). "Research has shown that ODF1 deletion impairs the generation of ODFs, the linkage piece and MS, resulting in sperm head separation and male infertility." (PMID 37371084, 2023). "We further analyzed the relationship between downregulated proteins and human reproductive diseases by DisGeNET and Cytoscape and found that proteins such as Odf1, Odf1, and Akap4 were involved in asthenozoospermia, teratozoospermia, and male infertility." (PMID 34268309, 2021). "The depletion of ODF1 by homologous recombination in mice led to male infertility." (PMID 36142191, 2022). "Sperm decapitation and male infertility were also observed when the outer dense fibre protein ODF1 or one of its interacting proteins centrosomal protein coiled-coil domain containing 42 (CCDC42) or the testis-specific SUN-domain protein SPAG4L/SUN5 were mutated." (PMID 32859975, 2020). "This section will briefly highlight the role of the eight (TNP1, TNP2, PDHA2, LDHC, SPINK2, ODF1, ODF2, and PCDHB3) common DEGs in male infertility as obtained from our findings." (PMID 35207567, 2022). "Although the decapitation of Odf1-deficient sperm was discovered as a cause of male infertility, the development of the HTCA in the absence of ODF1 has not yet been studied." (PMID 36142191, 2022). "Collectively, these results indicated that these proteins AKAP4, ODF1, ODF2, GAPDHS, SPESP1, and ACTRT2 were significantly down-regulated after heat treatment of scrotum, suggesting that these proteins may serve as the biomarkers for scrotal heat treatment-induced male infertility." (PMID 32787870, 2020). "It has been confirmed that the lack of outer dense fiber protein 1 (ODF1) is a marker and potential driver of idiopathic male infertility." (PMID 34221106, 2021).
infertile (7 papers, 2019 to 2025). "Investigations in male mice have found that loss-of-function mutations in genes involved in the production of headless spermatozoa, such as Spata6, Hook1, Prss21, Oaz3, and Odf1, can cause fertility reduction or infertility." (PMID 36028792, 2022). "ODF1 deficiency in male mice caused sperm decapitation and infertility." (PMID 36142191, 2022). "The sperm of infertile men with severely reduced ODF1 levels are easily decapitated during mild stress treatment, indicating weakened head–tail attachment." (PMID 36142191, 2022). "The inactivation of Fu in male germ cells led to infertility with numerous sperm abnormalities, such as decapitation, which is reminiscent of ODF1 depletion, while OIP1 has largely been uncharacterised." (PMID 36142191, 2022). "Targeted deletion of the Odf1 gene in mice revealed infertility in males in the homozygous condition, whereas females were not affected at all." (PMID 34571916, 2021). "A reduction in ODF1 protein was found in the semen of infertile men, and after stress treatment, sperm easily decapitate." (PMID 34571916, 2021). "Antibodies against ENO1, ALDOA, GAPDH, and ODF1 were also detected in human semen from infertile men." (PMID 34576131, 2021). "Mutations in centrosomal proteins such as Cep112, Cep250, Cntrob, and Odf1 result in defects in head-tail attachment and can lead to headless sperm and non-obstructive azoospermia that contributes to infertility." (PMID 40294089, 2025).
asthenozoospermia (3 papers, 2018 to 2022). "Western blotting showed that the expression levels of ODF components (Odf1, 2, 3, 4) were indeed down‐regulated in asthenozoospermia." (PMID 29168316, 2018).
Azoospermia (1 paper, 2025). Absence of any measurable level of sperm,whereby spermatozoa cannot be observed even after centrifugation of the semen pellet. "These centrosome components are critical for maintaining the head-tail attachment, as exemplified by the fact that mutation of centrosomal genes Cep112, Cep250, Cntrob, and Odf1, lead to acephalic spermatozoa (headless sperm) and non-obstructive azoospermia." (PMID 40294089, 2025).
cataract (1 paper, 2023). Partial or complete opacity of the crystalline lens of one or both eyes that decreases visual acuity and eventually results in blindness. "Lastly, although functional models are needed to prove the pathogenicity of the variants, the important role played by the HSPE1 and ODF1 genes in the lens and the de novo presence of the variants in the proband led us to propose both genes as causal for pediatric cataracts." (PMID 37511188, 2023).
Globozoospermia (1 paper, 2017). Any structural anomaly of the acrosome resulting in a round sperm head. "Male mice deficient in SUN4 are infertile due to globozoospermia, and SUN4 can bind to ODF1 (outer dense fiber protein 1), a sperm flagellum protein, suggesting that it might function in either nuclear remodeling or sperm integrity during spermiogenesis." (PMID 28945193, 2017).
lymphoma (1 paper, 2020). A malignant (clonal) proliferation of B- lymphocytes or T- lymphocytes which involves the lymph nodes, bone marrow and/or extranodal sites.
tumours (1 paper, 2018). "Incremented transcripts levels of HSPB1, HSPB9 and HSPB11 were observed in most BRCA subtypes, CRYAA was upregulated only in Basal subtype and ODF1 showed an increased expression in Luminal A tumours that was not significant by the Deseq2 method." (PMID 29954368, 2018).
ODF1 also shares sentences with these, for which no sentence is quoted: teratozoospermia (2 papers); bladder urothelial carcinoma (1); cancer (1); hepatocellular carcinoma (1); reproductive diseases (1).